MTOR (mechanistic target of rapamycin kinase)
Diseases named in the same sentence as MTOR in open-access papers (continued):
Sharing a sentence is not in itself a finding about the gene and the disease.
cancer (continued). "Specifically, diverse signaling pathways were found associated with CRNDE effect in cancers, such as the Wnt/β-catenin, PI3K/AKT/mTOR, Ras/mitogen-activated protein kinase (MAPK) and Notch1 signaling pathways." (PMID 32435153, 2020). "First, reduced blood insulin concentrations at the cancer cell membrane results in less binding to the insulin receptor with resulting downstream inhibition of the PI3K-Akt-mTOR (PAM) signaling cascade, as well as the RAS-RAF-MEK-ERK pathway." (PMID 33270630, 2020). "In most types of cancer GLUT-1 is over-expressed suggesting t that GLUT-1 over-expression under the influence of interrupted mTOR signaling cascade results in the activation of oncogenes such as the c-MYC and HIF-1α." (PMID 33292283, 2020). "The PI3K/Akt/mTOR pathway is central in cell homeostasis maintenance and metabolism regulation and is altered in several cancer types, including NSCLC." (PMID 33114576, 2020). "We focus mainly on cross-talk between MAPK/ERK, Hippo/MST and PI3K/AKT/MTOR signaling pathways in various cancer cells and discuss interplay between these pathways in the context of current cancer therapies." (PMID 32375238, 2020). "These previous findings indicate the crosstalk between AKT/mTOR and Wnt/β-catenin signaling pathways, and the regulation of these two pathways has also been reported in several cancers." (PMID 31682716, 2020). "ATP-competitive inhibitors of mTOR, which can block both the mTORC1 and mTORC2 complexes, also exert anti-cancer effects in GBM 37-39." (PMID 33162811, 2020). "AMPK/mTOR signaling pathway is dysregulated in most human cancers and has been considered a promising therapeutic target against cancers." (PMID 32943998, 2020). "The first one is a phase II clinical trial on everolimus in cancer patients with TSC1 and TSC2 mutation or activating MTOR mutation." (PMID 32850962, 2020). "Loss of either mTOR or AKT significantly suppresses prostate tumorigenesis in a PTEN-deficient model, suggesting that mTOR pathway is an attractive target for cancer treatment." (PMID 31685947, 2020). "The mammalian target of rapamycin (mTOR) signaling pathway is involved in many hallmarks of cancer including cell growth, metabolism re-programming, proliferation and inhibition of apoptosis." (PMID 32070029, 2020). "The in vitro approach used the SCC131 oral cancer cell line to investigate how gedunin, alone or combined with epalrestat, prevented the hallmarks of cancer by inhibiting ARase and the associated downstream PI3K/Akt/mTOR/ERK/NF-κB signaling axis." (PMID 31979346, 2020). "Although signal transducer and activator of transcription 3 (STAT3) and mTOR pathways play crucial roles in tumorigenesis, studies are underway to investigate cross‐talk between the two pathways in cancer cells." (PMID 32495998, 2020). "Consistent with their role in apoptosis suppression, cell proliferation, metabolism and anabolic reactions, the interconnected PI3K–AKT and mTOR pathways are hyperactivated in almost 40% of all human cancers." (PMID 31819197, 2020). "In order to better-characterize the piperazine compounds and move forward in our selection of a top cancer therapeutic candidate, we measured the absolute response of small molecules binding to the human mTOR protein with bio-layer interferometry (BLI)." (PMID 33255358, 2020). "The lack of lysosomal acid lipases, the enzymes involved in lipophagic degradation, results in the promotion of cancer growth and metastasis through the mTOR-dependent activation of myeloid-derived suppressor cells." (PMID 33364196, 2020). "This seems to confirm the role of AMPK/mTOR signaling pathway in the mechanism of the action of metformin, indicating its potential use in anti-cancer therapy." (PMID 31952173, 2020). "Once activated, Akt activation of the mTOR pathway leads to increased cell proliferation and reduced cell apoptosis involved in the pathogenesis of cancers." (PMID 33520990, 2020).
cancer (continued). "Liver kinase B (LKB)-AMP-activated protein kinase (AMPK) and mTOR are reported to be the main targets of metformin in relation to its ability to prevent cancer cell proliferation." (PMID 33375360, 2020). "Our results indicate that cardamonin suppresses cancer cell growth by inducing G2/M phase arrest and apoptosis through targeted inhibition of NF-κB and mTOR pathways." (PMID 33234722, 2020). "Since the mTOR pathway is dysregulated in many cancers, inhibition of mTOR represents a compelling therapeutic target for cancer treatment." (PMID 33067464, 2020). "The mTOR is one of the well-studied down-stream targets of Akt and many studies have shown that the PI3K/Akt/mTOR pathway plays important roles in cancer, particularly cancer cell survival, growth and apoptosis resistance." (PMID 32802178, 2020). "PI3K-AKT coupled with the downstream activation of mTOR pathways form a signaling network often altered in cancer as ovarian malignancies." (PMID 33329391, 2020). "In this regard, various studies have shown that curcumin exerts anti-cancer activity by inhibiting mTOR signaling, which among various effects activates the ATG pathway." (PMID 33092261, 2020). "Rapamycin is a macrolide antibiotic and inhibitor of the mechanistic target of rapamycin (mTOR) that exhibits potent anti-cancer and immunosuppressive activity originally used to prevent organ transplant rejection." (PMID 33343293, 2020). "The phosphatidylinositol-3 kinase (PI3K)-Akt-mammalian target of rapamycin (mTOR) pathway is very often activated in human cancer." (PMID 32106627, 2020). "Suppression of PI3Kγ–mTOR signal by PI3Kγ inhibition enhances tumor regression and prolongs survival in a synergistic fashion with PD-1 blockade in mouse models of cancer." (PMID 33114576, 2020). "The PI3K/AKT/mTOR pathway has been identified as a potential radiotherapy resistance inducing pathway in cancer." (PMID 32443649, 2020). "Mitogen Activated Protein Kinase-4 (MAPK-4) in different types of cancers is identified as an activating agent for AKT/mTOR signaling via alternative pathway." (PMID 33292283, 2020). "The data presented herein points to the crucial role of mTOR signaling in cancer progression, as well as the prospect of implementation of a successful combination of its inhibitors in cancer treatment." (PMID 31586300, 2020). "The AMPK/mTOR signalling pathway is a primary and key pathway in autophagy regulation that can coordinately determine the survival and autophagy of cancer cells and play a vital role in tumorigenesis." (PMID 32588529, 2020). "Combined pharmacological targeting of Mnk1 and mTOR shows greater growth inhibitory effects than the suppression of one of the pathways in many types of cancer cells." (PMID 32603377, 2020). "TRIM44 overexpression leads to high mTOR activity, which is consistent with observations of reduced mTOR signaling in cancer cell lines after siRNA knockdown of TRIM44." (PMID 32503466, 2020). "Furtheremore, several other compounds like honokiol, plumbagin, and small molecules such as pyrithione zinc (PYZ) have also demonstrated anti-cancer effects via the inhibition of the AKT/mTOR pathway in OC." (PMID 32384682, 2020). "The phosphoinositide 3-kinase (PI3K) and its downstream kinases, such as AKT and mTOR, modulate numerous programmed signaling pathways involved in cell survival and cancer progression." (PMID 32102330, 2020). "It is important to point out that while mTOR inhibitors, such as rapamycin analogs (i.e., rapalog), have been approved in the clinic to treat cancer, NFκB inhibitors efficacy as therapeutics is limited because of the host toxicity." (PMID 33202944, 2020).
cancer (continued). "Dysfunction of the PI3K/Akt/mTOR signaling pathway has been shown in pro-fibrotic diseases including cancer, and pulmonary and cardiac fibrosis." (PMID 33375386, 2020). "In this review, we discuss the mTOR signaling pathway cascade, focusing on the immune cell chemotaxis and function in human cancers." (PMID 32483450, 2020). "Several other PI3K and mTOR inhibitors have been approved for clinical use against different cancer types." (PMID 33316942, 2020). "PP242, an inhibitor of mechanistic target of rapamycin (mTOR), displays potent anticancer effects against various cancer types." (PMID 33067464, 2020). "KEGG pathway enrichment analyses revealed that these PCGs were enriched in the mTOR, AMPK, and VEGF signaling pathways, all of which are closely linked to cancer development and progression." (PMID 33228611, 2020). "The dysregulation of both pathways plays a role in the development and progression of a variety of cancers, and therefore, Hh and mTOR are targets for clinical treatments." (PMID 32751882, 2020). "MTOR inhibitors are actively investigated in preclinical cancer cell line and mouse models of GBM with various success." (PMID 32938364, 2020). "In conclusion, epalrestat heightens sorafenib's anti-cancer effects via blocking the mTOR pathway, thus inducing cell cycle arrest, apoptosis, and autophagy." (PMID 32547320, 2020). "The signaling network defined by phosphoinositide 3-kinase (PI3K), AKT, and mammalian target of rapamycin (mTOR) controls most hallmarks of cancer, including cell cycle progression, survival, metabolism, motility, and genomic instability." (PMID 32792943, 2020). "The AKT and mTOR constitutive activation confers drug resistance to many types of cancers, including NSCLC." (PMID 33520990, 2020). "Recently, new mTOR kinase inhibitors were developed that are more effective than rapamycin in cancer therapy." (PMID 33330509, 2020). "Since the PI3K/Akt pathway plays a key role in the development of many cancers, including PCa, inhibition of mTOR is widely considered a promising treatment many cancer patients." (PMID 32645691, 2020). "The miR-99b/mTOR and miR-99b/κB-Ras2 axis was also verified in TAMs of tumor-bearing mice and patients with live cancer." (PMID 32948650, 2020). "Other research groups have identified an astrocyte-specific mTOR complex and a rapamycin insensitive mTOR complex in human cancer cells." (PMID 33364499, 2020). "In human cancers, the autophagic process is usually suppressed in vitro and in vivo by the constitutively active Akt and its downstream target mTOR." (PMID 32410999, 2020). "The phosphatidylinositide 3 kinases (PI3Ks) and their downstream mediators AKT and mammalian target of rapamycin (mTOR) are central regulators of glycolysis, cancer metabolism, and cancer cell proliferation." (PMID 32296634, 2020). "In cancer, the mTOR has been shown to be an important player in the dysregulation of cap-dependent translation." (PMID 32823598, 2020). "The activation of AMPK as a nutrient sensor in some previous studies has been found to primarily downregulate mTOR activity in cancers." (PMID 32782783, 2020). "AMPK can either counteract growth-stimulating signaling mediated by mTOR activation or act as a metabolic survival factor in cancer cells, depending on different cancer cell types and other compensations within the cell." (PMID 33330475, 2020). "Accumulating evidence points to the role of the mTOR pathway in the regulation of the circadian system, as well as in various pathologies including cancer." (PMID 32295075, 2020). "Rapamycin (Rapa) is an mTOR inhibitor that has shown anti-tumor activity in several human cancers and acts downstream of the phosphoinositide 3-kinase (PI3K) pathway." (PMID 33114161, 2020). "AKT/mTOR has been confirmed as an important signaling pathway which promotes the growth of cancer stem cells(CSCs)." (PMID 32351329, 2020).
cancer (continued). "Infiltrating macrophages can induce epithelial-mesenchymal transformation by activating the AKT/mTOR signal, increasing the cancer stem cell-like population, leading to increased invasion of ccRCC cells." (PMID 33665156, 2020). "As part of the mTORC1 and mTORC2 complexes, mTOR has key roles in several pathways involved in human cancer, which has stimulated interest in mTOR inhibitors." (PMID 32317694, 2020). "A precursor of miR-99a was previously involved in apoptosis in cancer research, and its overexpression inversely correlated with mTOR expression enhancing apoptosis." (PMID 32887419, 2020). "Since the discovery of PIK3CA mutations in cancer, pharmacologic inhibitors of PI3K, mTOR, and AKT are in different stages of clinical development and trial." (PMID 32350708, 2020). "Two main nutrient sensing proteins implicated in cancer are AMP-activated protein kinase (AMPK) and the mammalian target of rapamycin (mTOR)." (PMID 32292719, 2020). "Rapamycin (sirolimus) is a macrolide product of Streptomyces hygroscopicus that inhibits mammalian target of rapamycin (mTOR) making it an effective immunosuppressant for treatment of allograft rejection and several cancers." (PMID 32751576, 2020). "The autophagy process with mTOR activation leads to extended cancer cell survival, which is stabilized, leading to drug resistance." (PMID 32883024, 2020). "In several cancer cells such as; gastrointestinal cancer cells and liver tumor cells, it was shown that mTOR when suppressed, helps in the proliferation of CSCs." (PMID 32351329, 2020). "Autocrine/paracrine signaling generally helps in the activation of PI3K/mTOR signaling pathway in cancers." (PMID 32351329, 2020). "The PI3K/mTOR pathway is a promising chemotherapeutic target, which is usually activated in many cancers." (PMID 33375363, 2020). "The elevated incidence of drug-induced ILD among those who received an mTOR inhibitor combined with trastuzumab is consistent with previous studies demonstrating associations between mTOR inhibitors and ILD among cancer patients." (PMID 32591987, 2020). "Aberrant signaling of mTOR is involved in many pathological states, such as cancer, cardiovascular disease, inflammation, autoimmunity, and metabolic disorders." (PMID 32574238, 2020). "We also found that RRS1 enhanced AKT/mTOR signaling activity, which is frequently activated in various cancers." (PMID 33204686, 2020). "Two out of three identified inhibitors target the oncogenic AKT/mTOR pathway that supports cancer cell growth and survival." (PMID 33042258, 2020). "Here, we also evaluated the functional relationships between miR-3135b and AKT1/mTOR signaling which is active in almost all cancers." (PMID 32601379, 2020). "The well-known mTOR/p70S6K signaling pathway is activated in many human cancers and plays an important role in cell survival and cell cycle progression." (PMID 32098126, 2020). "These include alterations that are common across multiple cancers, such as aneuploidy, TERT mutations, and activation of the RAS-RAF-MEK-ERK/JNK and PI3K/AKT/mTOR pathways." (PMID 32485873, 2020). "Inhibition of Wnt/β-catenin and phosphatidylinositol 3-kinase (PI3K)/Akt/mechanistic target of rapamycin (mTOR) pathways is considered a possible innovative therapeutic strategy for cancer treatment." (PMID 32046053, 2020). "More importantly, mTOR is one of the critical signaling hubs that are responsible for cancer cell growth and ageing." (PMID 32887218, 2020).
cancer (continued). "Somatic aberrations of PI3K/AKT/mTOR pathway genes have been frequently observed, in various cancers." (PMID 33247671, 2020). "Phosphoinositide-3-kinase (PI3K)/phosphatase and tensin homolog (PTEN)/Akt/ mammalian target of rapamycin (mTOR) signaling represents another pathway that is dysregulated in different types of cancer and can be hit by flavonoid compounds." (PMID 32268584, 2020). "The AKT/mTOR pathway plays an essential role in regulating the formation of blood vessels in both normal and cancer tissues." (PMID 32384682, 2020). "The combination of PI3K/Akt/mTOR inhibitors with Bcl-2 inhibitors has been examined in several preclinical cancer models." (PMID 32932888, 2020). "The solvent dependence properties of AZD2014 make it suitable to be used to detect and quantify its cellular uptake and cellular location in living cells in relation to studying directly its role as an mTOR inhibitor for treatment of cancer." (PMID 33142217, 2020). "Although both the STAT3 and mTOR pathways play crucial roles in tumorigenesis, studies are underway to investigate cross‐talk between the two pathways in cancer cells." (PMID 32495998, 2020). "Our previous study on different types of cancer cells which suffering nutrient stress had proved that the molecular mechanism of Guttiferone K-induced autophagy involved Akt/mTOR inhibition." (PMID 33100904, 2020). "There is ample evidence from preclinical studies to suggest that direct pharmacological inhibition of the PI3K/AKT/mTOR pathway components can radiosensitise different types of cancer cells." (PMID 32443649, 2020). "The evidence of PRR14 overexpression activating the PI3K/AKT/mTOR signaling pathway in other types of cancer is needed." (PMID 32541902, 2020). "Dysregulation of the mTOR signaling is involved in some of the cancer hallmarks, and thus the mTOR pathway is an important target for the development of a new anticancer therapy." (PMID 31586300, 2020). "The well characterized AKT/mTOR pathway is an attractive therapeutic target that contributes to the initiation and maintenance of cancer." (PMID 32913473, 2020). "The mTOR complexes can be pharmacologically inhibited by mTORi to promote the autophagy pathway and have been approved for use in the treatment of cancer." (PMID 32823598, 2020). "Aberrant mTOR signaling occurs frequently in cancers, so mTOR has become an attractive target for cancer therapy." (PMID 32541839, 2020). "Some well-appreciated cancer-related pathways were identified, such as Notch, mTOR, and Hedgehog signaling pathways." (PMID 33584787, 2020). "Various studies suggest that the PI3K/AKT/mTOR pathway is frequently activated in human cancers, including endometrial, and that the kinases involved are rational targets for the treatment of tumors." (PMID 32443471, 2020). "Taken together, our results demonstrated that the PI3K/Akt/mTOR pathway was most closely related to m6A in cancer and m6A modification sites were generally distributed in the PI3K/Akt and mTOR pathways." (PMID 32863943, 2020). "Collectively, our data argue that the expression of autophagy regulatory proteins, Beclin1 and ATG5, together with inactivation of mTOR, play key roles in mediating at least fifty percent of the anti-cancer actions of [602 + doxorubicin]." (PMID 32983965, 2020). "Mechanistic target of rapamycin (mTOR) signaling is correlated with cell apoptosis in a variety of cancers." (PMID 33336000, 2020). "Pitavastatin limits the migration and proliferation of cancer cells by the inhibition of angiogenesis via PI3K/Akt/mTOR downregulation." (PMID 32380783, 2020). "We also predict three most effective metabolic therapeutic targets for cancer oscillation as +mTOR, +PTEN, and +PDH." (PMID 32276228, 2020).